EPO (erythropoietin)
Diseases named in the same sentence as EPO in open-access papers (continued):
Sharing a sentence is not in itself a finding about the gene and the disease.
microcytic anemia (6 papers, 2017 to 2025). Anemia in which the red blood cell volume is decreased. "HUS-associated hemolytic anemia transitioned to non-hemolytic microcytic anemia along with unchanged erythropoietin levels after 21 days." (PMID 39450175, 2024). "In 2011, the search for the physiological function of MT2 has become even more interesting by the observation that the administration of erythropoietin (EPO) fails to correct the microcytic anemia present in Tmprss6-mutated mice." (PMID 33800732, 2021). "Patients with TMPRSS6 mutations display microcytic anemia which does not respond to EPO administration." (PMID 29073189, 2017). "Serum EPO levels were inappropriately low in both Col4a3KO and CPD mice, and despite increases in circulating iron and iron stores, CPD mice showed a similar degree of microcytic anemia as Col4a3KO, assessed by reduced hemoglobin, red blood cell number, hematocrit and mean corpuscular volume." (PMID 34334787, 2021).
obstructive sleep apnea (6 papers, 2015 to 2025). "Despite normal erythropoietin levels and mild obstructive sleep apnea, her hemoglobin (17 g/dL) and hematocrit (52%) remained elevated." (PMID 40255807, 2025).
retinal disease (6 papers, 2014 to 2022). "In order to study further the therapeutic mechanisms underlying EPO treatment for retinal diseases, we examined the effect of EPO on retinal capillary dropout and pathological neovascularization in RCS rats." (PMID 25119659, 2014). "Multiple laboratories have effectively used this split vector approach in preclinical models: first for the delivery of the erythropoietin genomic locus, but later for retinal disease genes caused by variants in the MYO7A gene (Usher syndrome, type 1B) and the ABCA4 gene (Stargardt disease)." (PMID 34768969, 2021). "Laboratory studies showed that EPO can treat retinal disease for adult mice through the inhibition of apoptosis." (PMID 36077032, 2022). "Our results suggest that EPO has therapeutic potentials in treatment of neuronal and vascular pathology in retinal disease." (PMID 25119659, 2014). "Taken together, our results suggest that EPO has therapeutic potentials in treatment of neuronal and vascular pathology in retinal disease." (PMID 25119659, 2014). "Our results warrant further investigation of EPO to treat neuronal and vascular pathology in retinal disease." (PMID 25119659, 2014). "Because of neuro and tissue-protective mechanisms, EPO may inhibit apoptosis, thereby leading to a beneficial effect in the treatment of retinal disease." (PMID 36077032, 2022). "Secondly, timing and dose are crucial for EPO treatment of retinal diseases." (PMID 28289375, 2017). "Hence, before the extension to the in vivo studies to further verify the MSC-EPO-mediated neuroprotective activity in a retinal disease animal model, it is vital to establish a stable clone of transduced MSC-EPO and determine the minimal amount of EPO sufficient to exert the neuroprotective action." (PMID 30108483, 2018). "It does not address the question whether exogenous EPO is beneficial in retinal diseases." (PMID 32785675, 2020).
sarcoidosis (6 papers, 2012 to 2025). Sarcoidosis is a multisystemic disorder of unknown cause characterized by the formation of immune granulomas in involved organs. "ARA290, a non- erythropoietic analogue of EPO, showed a significant improvement of neuropathic symptoms in patients with sarcoidosis in a phase II clinical trial." (PMID 25422898, 2014). "Novel therapeutic agents such as ARA 290, a nonhematopoietic erythropoietin analogue with potent anti-inflammatory and tissue protective properties, are interesting to explore in the treatment of SFN in sarcoidosis." (PMID 23304492, 2012).
thyroid diseases (6 papers, 2016 to 2025). "They suggested that thyroid diseases may affect hematopoiesis and thyroid hormone deficiency could lead to bone marrow repression and/or a decrease in erythropoietin production due to reduced O2 requirements." (PMID 38344555, 2024). "It is believed that thyroid diseases affect the process of hematopoiesis and thyroid hormone deficiency may lead to bone marrow repression and/or decrease in erythropoietin production due to the reduction of O2 requirements." (PMID 26819633, 2016). "This could be because thyroid disease often leads to bone marrow suppression, which in turn may decrease erythropoietin production." (PMID 40315206, 2025). "Moreover, thyroid disorders may have indirect effects on erythropoiesis by inducing gene expression and secretion of erythropoietin from the kidney." (PMID 34449542, 2021).
beta thalassemia (5 papers, 2010 to 2023). Beta-thalassemia (BT) is characterized by deficiency (Beta+) or absence (Beta0) of synthesis of the beta globin chains of hemoglobin (Hb). "Elevated EPO production is seen in animals affected with beta-thalassemia." (PMID 34754662, 2021). "Our results agree with a recent study investigating the EPO-ERFE-hepcidin pathway in PKD, HS, and beta-thalassemia patients." (PMID 36927785, 2023).
chronic mountain sickness (5 papers, 2017 to 2025). A pathological condition resulting from chronic exposure to hypoxia at high altitude. "Although expression of hypoxia-inducible factor 1α (HIF-1α) and EPOR does not differ between chronic mountain sickness patients and control subjects, the expression of HIF-2α and EPO is higher in the bone marrow cells of chronic mountain sickness patients than in controls." (PMID 28703764, 2017). "Von Hippel-Lindau (VHL) methylation has been shown to upregulate the hypoxia-inducible factor-1α (HIF-1α)/erythropoietin (EPO) pathway in rat bone marrow, leading to excessive red blood cell proliferation in chronic mountain sickness." (PMID 40722939, 2025).
cyst (5 papers, 2014 to 2024). A sac-like closed membranous structure that may be empty or contain fluid or amorphous material. "15, 18, S-HB associated cyst fluid samples (n = 14) had detectable levels of EPO (9.98 ± 10.10, range 1.72–33.9 pg/mL)." (PMID 27748427, 2016). "Interstitial cells adjacent to proximal tubular cysts in ADPKD patients produce erythropoietin independently of the oxygen pressure or the pH of the cyst fluid, two physiological parameters that affect erythropoietin production in the normal kidney." (PMID 38427307, 2024). "In the present study, cyst fluid concentrations of testosterone and growth hormone correlated with tumor size, whereas the concentration of erythropoietin correlated inversely with patient survival." (PMID 35659255, 2022). "Concentrations of erythropoietin and estradiol (in men) were higher in cyst fluid than in serum, suggesting formation by tumor or brain tissue." (PMID 35659255, 2022). "In contrast, the concentration of erythropoietin and (in male patients) estradiol was significantly higher in cyst fluid than in serum." (PMID 35659255, 2022). "A 50 ml aliquot of the serum samples and cyst fluid was used for the EPO immunoassay, which was performed in duplicate." (PMID 25295086, 2014). "EPO expression was demonstrated in RCC and cyst epithelial cells using immunohistochemistry, revealing extremely high EPO levels in the cyst fluid." (PMID 25295086, 2014). "Analysis of cyst fluid from 18 ADPKD patients showed a positive correlation between the erythropoietin content of the cysts and the hormone levels in the serum, indicating that the erythropoietin level in the cysts reflects the kidneys' erythropoietin production capacity." (PMID 38427307, 2024). "Survival correlated inversely with cyst fluid concentration of erythropoietin." (PMID 35659255, 2022). "As the production of EPO was observed in the cyst walls of the nephrectomized kidney and as bilateral elevation of sEPO level was demonstrated in the renal vein sampling, it is possible that the EPO may have been produced by cysts in the contralateral kidney." (PMID 25295086, 2014). "In cyst fluid from 25 patients with cystic glioblastomas (nine women and 16 men), several hormones were present: IGF-1, insulin, erythropoietin, growth hormone, testosterone, estradiol, and free triiodothyronine." (PMID 35659255, 2022). "In previous studies, EPO production has been observed in RCC cells and epithelial cells in the cyst wall of patients with RCC arising from ACDK." (PMID 25295086, 2014). "In the present case, EPO production was also demonstrated by immunohistochemical analysis in the RCC and cyst epithelial cells." (PMID 25295086, 2014). "Cyst fluid levels of IGF-1 and growth hormone correlated with cyst fluid levels of serum proteins, suggesting the importance of BBB dysfunction, whereas levels of erythropoietin and insulin did not correlate with serum protein levels in cyst fluid." (PMID 35659255, 2022). "Furthermore, we found that EPO is detectable in cyst fluid from S-HB (n = 14), while absent in CSF (n = 1)." (PMID 27748427, 2016). "Taken together, these findings indicate that S-HB may release EPO focally (cyst fluid, but not in CSF), with no discernible systemic effects (change in serum EPO and Hgb)." (PMID 27748427, 2016).
diabetic neuropathy (5 papers, 2016 to 2024). A chronic, pathological complication associated with diabetes mellitus, where nerve damages are incurred due to diabetic microvascular injury involving small blood vessels that supply these nerves, resulting in peripheral and/or autonomic nerve dysfunction. "Conclusively, the overexpression of EPO promoted the therapeutic effects of MSC on diabetic neuropathy via inhibiting SC apoptosis." (PMID 28299330, 2017).
endometriosis (5 papers, 2013 to 2025). The growth of functional endometrial tissue in anatomic sites outside the uterine body. "It has also been demonstrated that EPO levels were increased in the peritoneal fluid of patients with endometriosis." (PMID 29916217, 2019). "Here, we aimed to examine the role of EPO and its receptor activation in the development of endometriosis in rats." (PMID 29916217, 2019). "Our histopathologic results in particular indicate that EPO is more effective than its receptor activator MIRCERA in the development endometriosis." (PMID 29916217, 2019). "In this context, we aimed to investigate the role of EPO treatment and its receptor activation in endometriosis in rats." (PMID 29916217, 2019). "The aim of the present study is to assess the potential effects of erythropoietin-producing hepatocellular carcinoma A3 (EPHA3) on endometriosis, with emphasis on the autophagy and apoptosis of macrophages via inhibition of the mammalian target of rapamycin (mTOR) signaling pathway." (PMID 31262977, 2019). "Here we provide evidence that EPO is a promising candidate for the treatment of endometriosis." (PMID 29916217, 2019). "We hypothesized that EPO and other agents could exert a therapeutic efficacy via their negative-feedback effect on EPO receptors, which have already been shown to play a critical role in the development of endometriosis." (PMID 29916217, 2019). "We aimed to demonstrate the effects of exogenously-administrated EPO, DARBE, and MIRCERA on the treatment of endometriosis." (PMID 29916217, 2019). "Animals were treated with EPO, darbepoietin (the synthetic form of EPO) or EPO’s receptor activator, methoxy polyethylene glycol-epoetin beta (MIRCERA), after development of endometriosis." (PMID 29916217, 2019). "It was a clinical study and it is not clear whether the increased EPO level was a part of the endogenous repair process after endometriosis." (PMID 29916217, 2019). "The decrease in lesion sizes and non-recurrence after stopping EPO injections led us to consider that exogenously-applied EPO could be used effectively in endometriosis." (PMID 29916217, 2019). "Other proangiogenic factors, namely, IL-8, hepatocyte growth factor (HGF), erythropoietin, angiogenin, macrophage migration inhibitory factor, neutrophil-activating factor, and TNF-α, are all found at increased concentrations in the peritoneal fluid of patients with endometriosis." (PMID 23766765, 2013). "In addition to the use of EPO, we also used darbopoetin alpha (DARBE), which is a synthetic form of EPO, and methoxy polyethylene glycol-epoetin beta (MIRCERA), a long-acting EPO receptor activator, in order to assess their possible effects on the pathogenesis of endometriosis." (PMID 29916217, 2019).
Hepatic steatosis (5 papers, 2015 to 2022). Steatosis is a term used to denote lipid accumulation within hepatocytes. "Erythropoietin plays a crucial role in regulation of erythropoiesis and has been shown to ameliorate fatty liver disease in animal models." (PMID 36119721, 2022). "Erythropoietin (EPO) alleviates hepatic steatosis by activating autophagy via SIRT1-dependent deacetylation of LC3." (PMID 31291980, 2019). "Mice that received erythropoietin showed increased level of SIRT1 and LC3 with alleviating hepatic steatosis." (PMID 35909524, 2022).
Hydrocephalus (5 papers, 2016 to 2025). Hydrocephalus is an active distension of the ventricular system of the brain resulting from inadequate passage of CSF from its point of production within the cerebral ventricles to its point of absorption into the systemic circulation. "In an animal hydrocephalus model, EPO treatment significantly mitigated the dilation of the cerebral ventricles in obstructive hydrocephalus by augmenting the expression of AQP4." (PMID 39944892, 2025). "In this study, we investigate a neuroprotective agent, erythropoietin (EPO), in animal hydrocephalus model and its potential reversal effects on hydrocephalus by altering the expression of aquaporin-4 (AQP4)." (PMID 29982881, 2018). "The effects of EPO on hydrocephalus were investigated by studying cerebral ventricle size and structural ependymal changes." (PMID 29982881, 2018). "Present study examines the role for EPO in modulating AQP4 water channels in experimental hydrocephalus." (PMID 29982881, 2018). "In order to identify a critical role of AQP4 in progression of hydrocephalus, we tried to gain insights into the potential mechanisms of protective effect of EPO." (PMID 29982881, 2018). "EPO treatment led to significant recovery of body weight of pups as compared to saline treated pups following induction of obstructive hydrocephalus." (PMID 29982881, 2018). "A retrospective analysis of extremely low birth weight infants treated with erythropoietin from 1993 to 1998 indicated that hydrocephalus requiring shunting occurred in 4.5 % of treated survivors and 7.0 % of controls." (PMID 26846184, 2016). "We therefore hypothesize that the severity and duration of hydrocephalus can be rescued by EPO-mediated upregulation of AQP4 by modifying CSF flow into the cerebral blood stream through AQP4 channels." (PMID 29982881, 2018). "It is noted that EPO treatment upregulates AQP4 expression and reduces dilated cerebral ventricles in kaolin-induced model of obstructive hydrocephalus in rat pups." (PMID 29982881, 2018). "We used this PHHP model to test whether systemic, extended high-dose neonatal treatment with EPO+MLT could promote recovery and prevent hydrocephalus." (PMID 30319361, 2018). "Together, our results show that EPO-mediated upregulation of AQP4 significantly reduces dilation of the cerebral ventricles in obstructive hydrocephalus pups and may lead to potential therapeutic options for hydrocephalus." (PMID 29982881, 2018). "Most importantly, use of a clinically viable regimen of endogenous neuroprotective agents EPO and MLT to prevent PHHP suggests that safe, economically sound, non-surgical treatments for hydrocephalus may be possible to transform the care of preterm infants with severe IVH in the near future." (PMID 30319361, 2018).
Hypothermia (5 papers, 2016 to 2024). Reduced body temperature due to failed thermoregulation. "Hypothermia might also affect regulation of EPO release from astrocytes via exosomes as another possible mechanism." (PMID 32359362, 2020).
Intraventricular hemorrhage (5 papers, 2013 to 2024). Bleeding into the ventricles of the brain. "Does treatment with high-dose, intravenous recombinant human erythropoietin for preterm infants with moderate to severe intraventricular hemorrhage (IVH) improve short- and long-term neurological outcomes?" (PMID 36459138, 2022). "This preliminary report of a randomized clinical trial assess the safety and short-term outcomes of high-dose erythropoietin in preterm infants with intraventricular hemorrhage." (PMID 36459138, 2022).
kidney cancer (5 papers, 2016 to 2026). Primary or metastatic malignant neoplasm involving the kidney. "On the contrary, it is known that kidney cancer cells can release a hormone called erythropoietin." (PMID 30862152, 2019).
leukopenia (5 papers, 2007 to 2024). "The mechanism of leukopenia in our patient may be related to the extremely high levels of erythropoietin seen in our patient." (PMID 18067664, 2007).
liver fibrosis (5 papers, 2022 to 2025). "The data suggest a role of MAPK in the EPO protective effect against the development of hepatic fibrosis." (PMID 37649466, 2023). "EPO attenuated hepatic fibrosis in a dosage-dependent way, as manifested by the diminution in serum alanine aminotransferase and aspartate aminotransferase activities, as well as the increase in albumin level." (PMID 37649466, 2023). "We document that these molecular events mediate the EPO effect in the inhibition of liver fibrosis and restoration of liver function." (PMID 37649466, 2023). "For this purpose, our goal was to investigate the potential therapeutic value of EPO against TAA-induced hepatic fibrosis by concentrating on TLR4 and PI3K/Akt signaling pathway modification." (PMID 37649466, 2023). "This study examined whether EPO affects thioacetamide (TAA)-induced liver fibrosis by concentrating on the Toll-like receptor 4 (TLR4) cascade and the phosphatidylinositol 3-kinase (PI3K)/Akt pathway as possible pathways." (PMID 37649466, 2023). "Overall, the research suggested that EPO could prevent TAA-induced hepatic fibrosis through upregulating the PI3K/Akt signaling cascade and downregulation the TLR4 downstream axis." (PMID 37649466, 2023). "Erythropoietin (EPO) is recognized for its function in erythropoiesis; however, its potential antifibrotic effect against liver fibrosis remains unknown." (PMID 37649466, 2023).
myeloid leukemia (5 papers, 2019 to 2024). A clonal proliferation of myeloid cells and their precursors in the bone marrow, peripheral blood, and spleen. "Human myelogenous leukemia K562 cells are EPO independent and can be chemically induced to undergo erythroid differentiation." (PMID 36895793, 2023). "K562 is a typical malignant cell line of myeloid leukemia, which committed erythroid differentiation without the presence of EPO." (PMID 38388899, 2024). "In this study, we show that EPO promotes the survival of DA3/EPOR myeloid leukemia cells treated with genotoxic and nongenotoxic agents." (PMID 30622244, 2019).
Myocardial fibrosis (5 papers, 2012 to 2023). "In vivo experiments revealed the PI3K/AKT/TLR4 signaling pathway causes myocardial fibrosis and weakens erythropoietin inflammation in the rat heart." (PMID 36836952, 2023).